SCGB1B2P (secretoglobin family 1B member 2, pseudogene)
Synonyms: SCGB4A1P
Gene: Long non-coding RNA gene on chromosome 19 (34,576,727 to 34,668,193, reverse strand). Ensembl gene ENSG00000268751.
Diseases named in the same sentence as SCGB1B2P in open-access papers:
SCGB1B2P is named in the same sentence as 2 diseases in open-access papers, as found by Europe PMC text mining. Sharing a sentence is not in itself a finding about the gene and the disease. The quoted sentences say what the papers report.
tumor (2 papers, 2023 to 2025). "Moreover, we identified five molecules (SCGB1B2P, SFRP2, POSTN, COL3A1, ENTPD6) that were universally overexpressed in medullary cells infiltrated by IBC tumours." (PMID 40624675, 2025).
SCGB1B2P also shares sentences with these, for which no sentence is quoted: breast carcinoma (1 paper).